RN7SL385P (RNA, 7SL, cytoplasmic 385, pseudogene)
Gene: Miscellaneous RNA gene on chromosome 22 (37,669,464 to 37,669,739, reverse strand). Ensembl gene ENSG00000241333.
Homologues: Orthologues: chimpanzee Metazoa_SRP (99% identical). Paralogues in human: RN7SL1 (84% identical), RN7SL2 (84% identical), RN7SL3 (83% identical), RN7SL126P (82% identical), RN7SL186P (80% identical), RN7SL788P (80% identical), RN7SL220P (80% identical), RN7SL386P (80% identical), RN7SL45P (80% identical), RN7SL218P (80% identical), RN7SL493P (80% identical), RN7SL7P (80% identical), and 703 more.